LEP (leptin)
Diseases named in the same sentence as LEP in open-access papers (continued):
Sharing a sentence is not in itself a finding about the gene and the disease.
breast cancer (continued). "In the context of the immune system and breast cancer, leptin is hypothesized to induce IL-18 expression both in TAMs (tumor-associated macrophages) and breast cancer cells." (PMID 34912237, 2021). "Leptin in several studies of animal models is associated with breast cancer tumorigenesis." (PMID 33482868, 2021). "Moreover, leptin also upregulated metastasis associated protein 1 (MTA1) in breast cancer cells that further contributed to the inactivation of GSK3β via Wnt1 signaling." (PMID 34588926, 2021). "Moreover, postmenopausal women with the highest waist circumference and leptin concentration are documented to have maximum risk of breast cancer." (PMID 34535145, 2021). "Leptin levels, both in circulating plasma or expression in breast cancer tissue, are reported to have association with breast cancer progression Leptin and leptin receptor are overexpressed in breast cancer tissue probably due to hypoxia, IGF, estradiol, and insulin overexposure." (PMID 33482868, 2021). "LEP was an unfavorable prognostic marker in cohorts of glioma, lung cancer, colorectal cancer, renal cancer, ovarian cancer, and melanoma, while in patients with thyroid cancer, pancreatic cancer, and breast cancer, high LEP levels were associated with favorable outcomes." (PMID 33799880, 2021). "Although a previous study claimed either no or even a negative correlation between the serum leptin levels and pre-menopausal breast cancer incidence, the interrelationship between leptin serum levels and breast cancer risk in post-menopausal women is well-established." (PMID 34588926, 2021). "The evolution of estrogen-dependent breast cancer is primarily caused by ER signals that can be activated by LEP signaling, which may explain the positive association between ER+ breast cancer patients in the current study and breast cancer recurrence." (PMID 34414945, 2021). "An overview of systematic reviews explored the association between circulating leptin levels and risk of breast cancer, and all of them showed an increased breast cancer risk with higher leptin levels in postmenopausal women, and the majority also found the same association in all women." (PMID 34210055, 2021). "Furthermore, leptin‐induced FFA release was significantly suppressed by 3‐MA or Bafilomycin A1 pretreatment, or LC3B gene silencing, suggesting that autophagy induction is implicated in intracellular FFA generation by leptin in breast cancer cells." (PMID 33226729, 2021). "In parallel, studies in breast cancer patients found an association between leptin and ObR overexpression with a chronic inflammatory status, conditioning T-cell immune responses (increase Th1- and decrease Th2-responses) and the activation of immune checkpoint inhibitors." (PMID 33644151, 2021). "Leptin plays an important role in breast cancer tumorigenesis and may be implicated in activation of the immune system." (PMID 34868066, 2021). "The presence of AA polymorphic homozygotes and GA heterozygotes may correlate with higher levels of leptin and obesity, and thus with a higher risk of breast cancer." (PMID 33864589, 2021). "One of the mechanisms through which leptin causes breast cancer progression is the regulation of breast cancer stem cell (CSC) activity by modulating the many signalling pathways (i.e., Notch, Wnt, mTOR, STAT3, HER2/Erb, and IGF pathways) and transcription factors (i.e., HIF-1 and NFκB)." (PMID 32033341, 2020). "Leptin and resistin are well-known adipokines linked to breast cancer." (PMID 32257945, 2020). "Indeed, long-term anastrozole treatment of breast cancer cells induced leptin and ObR overexpression, which was associated with constitutive activation of leptin downstream effectors." (PMID 32260113, 2020).
breast cancer (continued). "The molecular mechanisms underlying the association between increased adiposity and aggressive breast cancer phenotypes remain unclear, but likely involve the adipokines, leptin (LEP) and adiponectin (ADIPOQ), and their receptors (LEPR, ADIPOR1, ADIPOR2)." (PMID 32046756, 2020). "Due to the lack of a group with breast cancer without treatment in the present study, it could not exclude the possibility of alteration of adiponectin and leptin expression as the hidden risk factor involved in this phenomenon in these breast cancer women." (PMID 33086618, 2020). "The circulating levels of adipokines like leptin and adiponectin have been suggested as potential markers of increased risk for developing cardiovascular disorders and breast cancer but their potential role in the pathogenesis of these disorders remains obscure." (PMID 32555994, 2020). "However, elevated leptin levels are associated with breast cancer aggressiveness and a bad prognosis." (PMID 32512860, 2020). "In this prospective case-control study nested within the Mano a Mano Cohort Study, we assessed the risk of breast cancer with regard to plasma levels of c-peptide, gastric inhibitory polypeptide, insulin, leptin, monocyte chemoattractant protein-1, pancreatic polypeptide, and peptide YY." (PMID 31292496, 2019). "Also hyperglycemia seems to increase the risk of breast cancer in pre-malignant cells and to enhance cancer progression in malignant epithelial cells through leptin/IGF1 signaling." (PMID 31380268, 2019). "Moreover, leptin and its receptor were found to be overexpressed in breast cancer, especially in higher grade tumors and were associated with distant metastasis and poor prognosis." (PMID 30634494, 2019). "Conversely, associations for the DNAm-predictors of cystatin C and leptin were robust to adjustment and may be useful DNAm-based markers for predicting breast cancer." (PMID 31848323, 2019). "As expected, IL-18 was implicated in leptin-enhanced breast cancer cell invasion and migration." (PMID 31492049, 2019). "Although research on cystatin C and breast cancer is limited, prospective studies suggest leptin might be a marker of breast cancer risk." (PMID 31848323, 2019). "Based on the antagonistic impact on the risk of breast cancer, some authors have proposed that the adiponectin/leptin ratio may be more useful than the individual levels of adipokines for assessing the risk profile of breast cancer." (PMID 31380268, 2019). "Interestingly, among women age <51 years, leptin levels were inversely associated with breast cancer risk (OR = 0.49, 95% CI: 0.24, 0.82)." (PMID 31292496, 2019). "Although different epidemiological studies have reported contradictory results regarding the association between leptin concentrations and breast cancer, a meta-analysis of 23 studies has shown that leptin levels are positively associated with breast cancer risk." (PMID 30634494, 2019). "Moreover, overexpression of the receptor for leptin has been found in breast cancer and in particular for higher-grade tumors associated with metastasis and poor clinical prognosis." (PMID 31561459, 2019). "Importantly, leptin seems to be related to breast cancer risk in premenopausal obese women, however, controversy exists." (PMID 31671408, 2019). "Such reduction is particularly relevant to premenopausal or younger women since it can help explain why high leptin may lower breast cancer risk among them." (PMID 31292496, 2019). "A previous study suggested that leptin level was associated with the development of breast cancer." (PMID 31196966, 2019). "Interestingly, the DNAm-predictors of leptin and cystatin C that are components of DNAm GrimAge were strongly associated with breast cancer incidence, even after adjustment for breast cancer risk factors." (PMID 31848323, 2019). "In addition, among younger women, higher leptin levels were significantly associated with a decreased risk of breast cancer." (PMID 31292496, 2019).
breast cancer (continued). "For example, in a prospective case-control study nested within the Nurses’ Health Study II cohort, after adjusting for BMI at age 18 years, weight change from age 18 years to blood draw, and other breast cancer risk factors, plasma leptin was a protective factor for breast cancer." (PMID 31292496, 2019). "Increased IL-1β levels in a 3D model of breast cancer bone metastases were also associated with increased expression of adipokine/cytokine leptin, underling not only the critical role of IL-1β in the breast cancer bone metastatic niche but also in bone marrow adipose tissue." (PMID 31847214, 2019). "The importance of leptin signaling in breast carcinogenesis was then highlighted in another work, showing that this adipokine was able to sustain tumor progression in MMTV-Wnt-1 mice, while mammary tumor growth was inhibited in leptin-deficient mice (Lepob/ob)." (PMID 30634494, 2019). "A study of Iranian women with breast cancer showed a higher frequency of breast cancer development associated with the LEP G2548A polymorphism of the A allele, as compared to the control group; interestingly, the polymorphism of the G allele conferred a protective phenotype." (PMID 30404206, 2018). "Moreover, post-menopausal and pre-menopausal Mexican women appeared susceptible to develop breast cancer if the LEPR Q223R or the LEP G2548A polymorphisms, respectively, were present." (PMID 30404206, 2018). "For instance, leptin and its receptor have been demonstrated to facilitate the interaction between cells from the tumor microenvironment, such as cancer-associated fibroblasts and adipocytes, and breast cancer stem cells (BCSCs)." (PMID 28970834, 2017). "Leptin, a peptide hormone secreted from white adipocytes, may be an independent risk factor for breast cancer." (PMID 27926517, 2017). "In premenopausal women, this ADIPO:LEP breast cancer association is less clear." (PMID 28676553, 2017). "Breast cancer histotypes showed significant association with leptin immunostaining (P = 0.0001)." (PMID 29121911, 2017). "Although previous reports clearly indicate the crucial role of ER signaling in leptin-induced growth of breast cancer cells, the underlying molecular mechanisms are still largely unknown." (PMID 29312618, 2017). "Leptin plasma level seems a direct and independent biomarker of a breast cancer risk." (PMID 29254161, 2017). "For example, LEP, the top hub methylation feature affecting the largest number of gene expressions with total degree of 9, is found to be associated with basal-like or luminal A breast cancer subtypes." (PMID 28589855, 2017). "We carried out a case-control study to prospectively assess whether pre-diagnostic levels of CRP, TNF-α, IL-6, leptin, and adiponectin in plasma are associated with risk of developing breast cancer." (PMID 28983080, 2017). "Thus, the current study describes leptin immunoexpression in BC and evaluates the association between leptin phenotype and the clinical factors as well as follow-up data of breast cancer." (PMID 29121911, 2017). "Breast carcinoma stage was also significantly associated with leptin expression (P = 0.0291)." (PMID 29121911, 2017). "There were significant post-intervention changes for weight (>10% loss), fruit and vegetable consumption (+3.7 ± 4.3 servings/day), and physical activity (+1235 ± 832 kcal/week), and reductions in two biochemical mediators of breast cancer risk, fasting insulin (−16.7%) and leptin (−37.1%)." (PMID 27376159, 2016). "In addition, siPKM2 abolished EMT-associated marker expression and inhibited leptin-induced migration and invasion of those breast cancer cells." (PMID 27769315, 2016). "Data on the association of leptin with breast cancer risk are mixed." (PMID 27338371, 2016). "Considering the crucial role of leptin signaling in breast cancer in both mouse and human reports, weight loss-associated changes in leptin concentrations could play an important role in BBC prevention." (PMID 27042159, 2016).
breast cancer (continued). "In addition, leptin has been considered a cytokine associated to breast cancer proliferation too, with an important role in the breast cancer cellular microenvironment." (PMID 27415018, 2016). "To assess the effect of Leptin (-2548G/A) gene polymorphism on breast cancer susceptibility, we searched PUBMED, ISI Web of Knowledge, EMBASE, Chinese National Knowledge Infrastructure (CNKI) databases until September 2015 to identify eligible studies, without restriction." (PMID 26825898, 2016). "In addition, it was recently suggested that circulating leptin, resistin, and visfatin levels have some diagnostic values for breast cancer in postmenopausal women." (PMID 27293305, 2016). "High leptin levels have been found to increase breast cancer risk." (PMID 27588409, 2016). "This study aims to test this hypothesis and further investigate the molecular mechanism underlying leptin-mediated cancer promoting effects of M2 macrophages on breast cancer cells." (PMID 27588409, 2016). "The realization of the impact of hyperleptinemia associated with obese state on breast cancer incidence, behavior, and prognosis, has spurred a great interest in the development of effective strategies to inhibit multipartite leptin signaling and oncogenic functions." (PMID 26359358, 2015). "In addition, when SCID/beige mice were co-injected with MCF7 breast cancer cells with MSCs containing leptin shRNA, leptin levels in MSCs decreased and also caused a reduction in MCF7 tumor volume and fewer metastatic lesions in the lungs and livers of mice." (PMID 26694366, 2015). "Reports on the relationship of circulating levels of adiponectin and leptin to incident post-menopausal breast cancer are contradictory, and the association of breast cancer recurrence and survival with circulating concentrations of these adipokines is equally mixed." (PMID 26132992, 2015). "Leptin is the most prominent and best studied adipokine, and has been suggested to be implicated in the development of hormone-dependent malignancies including breast cancer." (PMID 26560078, 2015). "However, two clinical reports fail to link circulating leptin with breast cancer recurrence, although another has shown leptin to be associated with distant recurrence and death even when statistical models were adjusted for BMI and body weight." (PMID 26132992, 2015). "Leptin and adiponectin are two important adipokines associated with breast cancer." (PMID 25072025, 2014). "Indeed, both leptin and its receptor are overexpressed in breast cancer, especially in higher grade tumors and are associated with distant metastasis." (PMID 25505738, 2014). "Breast cancer risk is higher in obese postmenopausal women compared with postmenopausal women of a normal weight, and high leptin concentrations may contribute to this risk." (PMID 24959279, 2014). "Furthermore high levels of leptin in women correlate to an increased risk of breast cancer, metastatic tumor phenotype and poor prognosis." (PMID 25147760, 2014). "Increased leptin circulating levels associated with excess adiposity may also constitute a risk factor for breast cancer." (PMID 23964270, 2013). "The results indicated that higher leptin may be associated with increased incidence and development of breast cancer." (PMID 23826274, 2013). "Greater weight may be associated with breast cancer because it is associated with hormone levels likely to contribute to breast cancer including higher leptin levels, lower adiponectin levels, and higher estrogen levels." (PMID 23682336, 2013). "Many studies have investigated the association between serum leptin level and breast cancer." (PMID 23826274, 2013). "High plasma levels of leptin have been linked to breast cancer development." (PMID 24202338, 2013). "Indeed, clinical studies correlate high leptin levels and low adiponectin levels in women to an increased risk of breast cancer, metastatic tumor phenotype with poor prognosis." (PMID 23554900, 2013).
breast cancer (continued). "In addition, high leptin expression in human breast cancer was significantly associated with high Ki67 expression." (PMID 23272114, 2012). "Furthermore, the elegant work of Dr. Cleary's group has shown that obese mice with deficiency in leptin signaling (ob/ob or db/db) show a significantly lower incidence of mammary tumors than their lean littermates." (PMID 21731759, 2011). "Furthermore, obese patients with breast cancer exhibit a higher expression of this gene and higher levels of estrogen in breast tissue as a result of increased plasma leptin synthesis, which is caused by obesity." (PMID 22203527, 2011). "A large area of fatty breast tissue could also increase breast cancer risk through adipocytokines, such as leptin and adiponectin, which are secreted by the fat tissue." (PMID 22030015, 2011). "Some studies have reported that leptin stimulates the proliferation of normal and malignant breast epithelial cells and others have suggested that leptin levels may be associated with breast cancer as well as cancer at other sites." (PMID 19208204, 2009). "Leptin may have a role in breast cancer development, especially in postmenopausal women where body mass index (BMI) is a breast cancer risk factor." (PMID 19545414, 2009). "Similar to breast cancer, leptin and adiponectin are associated with endometrial cancer." (PMID 21566743, 2008). "However, very few epidemiologic studies have assessed leptin concentrations in relation to breast cancer risk." (PMID 17229323, 2007). "Thus, more epidemiological studies are clearly needed to confirm the leptin-breast cancer association in postmenopausal women." (PMID 17229323, 2007). "We hypothesized that in postmenopausal women, after controlling for well-known breast cancer risk factors, central fat would be strongly associated with serum leptin concentrations and the association with central body fat would be greater than for BMI." (PMID 17229323, 2007). "We hypothesize that these leptin and leptin receptor polymorphisms associated with higher leptin serum levels and overexpression of leptin in adipocytes, favour breast cancer development and aggressiveness." (PMID 16504019, 2006). "However, the most recent reports indicate that higher leptin serum levels are associated with advanced stage breast cancer." (PMID 16504019, 2006). "Moreover, the presence of the LEP (-2548) A allele showed a significant association with decreased disease-free survival in breast carcinoma patients, and the presence of the LEPR 223R allele showed a significant association with decreased overall survival." (PMID 16504019, 2006). "Our results indicated that the polymorphisms in LEP and LEPR genes are associated with increased breast cancer risk as well as disease progress, supporting our hypothesis for leptin involvement in cancer pathogenesis." (PMID 16504019, 2006). "Other possible hormones that could be mediating the effect of pregnancy weight gain on breast cancer risk include leptin." (PMID 15498103, 2004). "To date, the characterization of leptin’s role in breast cancer remains somewhat controversial and appears to be associated with body weight and women’s menopausal status, and to have an impact on signaling pathways involved in different molecularly typed breast cancers." (PMID 41269404, 2025). "Because high leptin levels are associated with an increased risk of breast cancer and may increase resistance to ET, as demonstrated in preclinical breast cancer models, it has been speculated that lowering leptin levels through weight loss may improve outcomes for breast cancer survivors." (PMID 39251829, 2024). "Overall, leptin and adiponectin have opposing effects on breast tumorigenesis and their ratio may be modulated particularly in people with high BMI as it significantly increases breast cancer risk and metastasis." (PMID 37800138, 2023).